ANXA5 (annexin A5)
Diseases named in the same sentence as ANXA5 in open-access papers (continued):
Sharing a sentence is not in itself a finding about the gene and the disease.
tumor (continued). "Human protein array analyses identified cellular targets of XON9, such as solute carrier family 3 member 2 (SLC3A2), annexin A5 (ANXA5), fatty acid synthase (FASN) or reticulon 4 (RTN4) involved notably in tumor progression, angiogenesis, cell growth or apoptosis." (PMID 41009747, 2025). "Furthermore, a survival analysis was conducted on the individual genes comprising the UBE2C+ tumour cell score, and it revealed statistically significant results for ITPRIP, GJA1, RUNX1T1, CD82, PAPSS2 and ANXA5." (PMID 38894657, 2024). "Functional experiments validated that ANXA5 downregulation influences tumour cell migration without affecting proliferation." (PMID 39400959, 2024). "Notably, the differences between tumor and normal cells in NUCB1 mRNA expression were more pronounced than for IRF4 and ANXA5." (PMID 36611989, 2023). "Finally, while we demonstrated that AnxA5-antigenic peptide fusion proteins have similar therapeutic antitumor effects against TC-1 and CT26 tumor models, further evaluations in additional tumor models is warranted to assess any potential treatment variations." (PMID 32111835, 2020). "Furthermore, the observed effect of ANXA5 expression interference, which impacts tumour cell migration without affecting proliferation, raises intriguing questions deserving of further in‐depth exploration." (PMID 39400959, 2024). "Thus, ANXA5, FKBP10, MSN, and PYGL might be presented by APCs to the T cells and recognized by the B cells to induce a tumor response." (PMID 34512630, 2021). "In a mouse model for ovarian cancer, the delivery of AnxA5 fused to an enzyme that converts selenomethionine to toxic methylselenol, in combination with anti-CD73 and anti-Ox40 as immunostimulants, strongly decreased tumour burden in mice with orthotopic metastatic ovarian cancers." (PMID 33810523, 2021). "Since Annexin A5 tumor uptake has shown promise to be a predictor of TRR, DFS and OS, Annexin A5 imaging could be used as a surrogate endpoint in clinical trials, subsequently lead to faster drug approval and even lower the economic burden on pharmaceutical industries." (PMID 24216991, 2013). "In addition, both CM presented a remarkable quantity of different proteins that have been associated with antioxidant and/or anti-inflammatory effects and may thus mediate the viability of non-tumor cells, such as AIFM1, ANXA5, CD9, CDH13, GDF15, GSR and TIMP2." (PMID 34884877, 2021). "However, we have increased size by using streptavidin and biotinylated anxA5 and cannot rule out that increasing size by other methods yielding complexes with different size, shape and surface charge have different relative contributions of PS-targeting to the overall uptake by the tumor." (PMID 24801051, 2014). "While AnxA5 administration alone following cisplatin treatment can rescue the immunosuppressive effects within the TME, cisplatin and AnxA5 treatment is not effective at controlling the growth of tumor and prolonging mouse survival." (PMID 32111835, 2020). "Tumor-bearing mice were then treated with intraperitoneal injection of cisplatin, intratumoral vaccination of HPV16-E7 long peptides, and/or intravenous administration of AnxA5 protein, with phosphate buffer saline (PBS) as negative controls." (PMID 32111835, 2020). "In this bioconjugate, the SWCNTs were functionalized with the protein annexin A5 (ANXA5), which binds with high affinity to the anionic phospholipid phosphatidylserine expressed externally on tumor cells and on endothelial cells of the tumor vasculature, but not on normal cells in the vasculature." (PMID 33411055, 2021).
cancer (637 papers, 2001 to 2026). A tumor composed of atypical neoplastic, often pleomorphic cells that invade other tissues. "Several studies have reported that high ANXA5 levels, as observed in the most severe form, are associated with significantly lower survival rates in various cancers, highlighting its critical role in proliferation, metastasis, and immune evasion." (PMID 41441336, 2025). "In the context of cancer, high ANXA5 expression has been associated with poor outcome in gliomas, hepatocarcinomas, bladder, colorectal and cutaneous squamous cell carcinomas." (PMID 36247003, 2022). "Further experimental analysis of HCC samples exhibited that the expression levels of KLF2 and ANXA5 were associated with immune cell infiltration and expression of PD-L1 in cancer tissues." (PMID 35992798, 2022). "A calcium-dependent phospholipid-binding annexin- annexin A5 (ANXA5) is associated with the generation, metastasis and development of various cancers." (PMID 35992798, 2022). "Similarly, dysregulated expression of AnxA5 has been implicated in the development, progression, metastasis, treatment and prognosis of a variety of cancers." (PMID 36123610, 2022). "An association between ANXA5 and several cancers has been assumed." (PMID 31703610, 2019). "In addition, ANXA5 was found to be associated with hepatocarcinoma, cervical carcinoma, colorectal cancer and other cancers." (PMID 27684953, 2016). "Therefore, this intriguing observation encourages investigating whether the role of ANXA2, and ANXA5 in the nucleus of cancer cells, either contribute to carcinogenesis or is associated with an anticancer mechanism." (PMID 37117324, 2023). "Based on risk factors, drug sensitivity screening, and the degree of differential expression between cancer and normal tissues, we have identified ANXA5, MARCKS, and SERPINE1 as candidates warranting further research." (PMID 38287304, 2024). "Annexin A5 radioligands were explored in multiple medical conditions including cancer, bacterial endocarditis, arthritis, chronic obstructive pulmonary disease, and carotid artery disease." (PMID 39204083, 2024). "It is evident that most of them are highly expressed in cancer, with ANXA5, SERPINE1, MARCKS, and MATN3 being particularly significant in their expression levels." (PMID 38287304, 2024). "Among 12 annexin A isoforms (annexin A1-11 and annexin A13), annexin A5 in particular has unphosphorylated short N-terminus which enables this protein to exhibit a wide range of functions such as signalling, cancer cell growth, and invasion." (PMID 38249992, 2024). "Multiple molecular imaging studies have used technetium-99m (99mTc)-labeled Annexin A5 in patients with cancer and rheumatic disease." (PMID 39204083, 2024). "By contrast, hybridization of these two cell types was impaired by annexin A5 knockdown, which supports the necessity of PS even in cancer cell-cell fusion." (PMID 37016404, 2023). "This includes functionally relevant proteins associated with LN metastasis in cancer such as KRT7, KRT19, SRI, NPM1, Annexin A2 (ANXA2), Annexin A5 (ANXA5)." (PMID 37142981, 2023). "This suggests that annexin A5 plays a dual role in cancer cell malignancy and depends on tissue specificity." (PMID 35805203, 2022). "This delicate interaction between muscle and cancer cells is accompanied by several processes: an increase in IL-4 and IL-13 secretion, an overexpression of annexin A5 and syncytin 1 and a noticeable fusion of cancer cells." (PMID 33841508, 2021). "The ability of AnxA5 to recognize PS exposed by apoptotic cells has been very valuable in cancer-related studies." (PMID 33810523, 2021). "Annexin A5 (anxA5) is a marker for apoptosis, but has also therapeutic potential in cardiovascular diseases, cancer, and, due to apoptotic mimicry, against dangerous viruses, which is limited by the short blood circulation." (PMID 34405304, 2021).
cancer (continued). "We also observed a modulation of the expression of annexin A5 (ANX5A) in both normal as well as in cancer cell lines." (PMID 34678978, 2021). "Our data support the use of AnxA5 following chemotherapy as a promising immune checkpoint inhibitor for cancer treatment." (PMID 32111835, 2020). "Our findings support the administration of AnxA5 following chemotherapy as a promising immune checkpoint inhibitor for cancer treatment." (PMID 32111835, 2020). "All of these details revealed in several in vitro studies suggest that Annexin A5 plays a key role in the subsistence and apoptosis of cancer cell." (PMID 32219016, 2020). "Nonetheless, there is recent evidence that annexin A5 is related to the efficacy of cancer therapies." (PMID 30774659, 2019). "As a calcium-dependent phospholipid binding annexin protein, annexin A5 (Anxa5) links to the progression, metastasis, survival, and prognosis of a variety of cancers." (PMID 29802377, 2018). "More scientific and clinical significances for investigating the role and action mechanism of ANXA5 in the progression and metastasis of human cancers and cancer cell lines should be addressed in the further." (PMID 29802377, 2018). "As described in‘Results’, our proteomics analysis have revealed that ANXA5 modulates multiple key pathways, which are relevant to cancer cell growth and metabolism." (PMID 27684953, 2016). "Recent data suggest that the invasion capacity, a main characteristic of tumors, is at least in part regulated by Annexin A5 in different cancer types." (PMID 24743186, 2014). "Radiolabeled anxA5 has been evaluated in clinical studies and the clinical experience, although promising, indicate that the anxA5 imaging protocol requires improvement in order to be applicable to a broad range of cancer types and treatment regimens." (PMID 24801051, 2014). "Pharmaceutical and diagnostic industries will thus have to play a key role in the scientific validation of 99mTc-HYNIC-Annexin A5 imaging in evaluating efficacy of anti-cancer therapies." (PMID 24216991, 2013). "In 2007, the group reports pre-treatment 99mTc-HYNIC-Annexin A5 SPECT imaging in 23 patients of various cancer types." (PMID 24216991, 2013). "99mTc-HYNIC-Annexin A5 imaging shows potency to predict efficacy of anti-cancer therapy and thereby bears the promise to assess therapy response in a personalized manner at an early stage in cancer treatment." (PMID 24216991, 2013). "Pan-cancer analysis revealed widespread high expression of ANXA5 in various types of tumors." (PMID 38287304, 2024). "So the ANXA5 administration following chemotherapy could be considered as a promising immune checkpoint inhibitor for cancer treatment." (PMID 37679418, 2023). "However, in our experimental setting, only annexin A5 showed consistently higher binding to cancer cell-derived m/lEVs (annexin A1+)." (PMID 36992223, 2023). "Here, we concluded that both GlaS and annexin A5 could recognize certain cancer cell-derived m/lEVs." (PMID 36992223, 2023). "According to this purpose, it has been demonstrated that ANXA5 may improve specific cancer cell targeting when combined with different therapeutic strategies, such as phototermal nanotubes, vaccine antigens, or enzyme-prodrug systems." (PMID 36247003, 2022). "Along these lines, fusion of AnxA5 with the peptide-major histocompatibility complex strongly augmented lymphocyte response, which could serve to improve immune modulation for cancer therapy." (PMID 33810523, 2021). "Whether the description of mechanisms related to membrane resealing in cancer cells was outside the scope of this study, some observations that we have done gave interesting clues on the role played by AnxA5 and AnxA6." (PMID 33311633, 2020). "We speculated that METF, acting on annexin A5, could represent a novel coadjuvant in cancer therapy." (PMID 30774659, 2019).
cancer (continued). "However, the underlying molecular regulation mechanism and clinical significance of Anxa5 in cancer progression and metastasis, especially in cancer lymphatic progression and metastasis, are poorly understood." (PMID 29802377, 2018). "At present, the research of Anxa5 in cancer lymphatic metastasis is limited." (PMID 29802377, 2018). "ANXA5 is widely distributed and abundantly expressed in cancer cells." (PMID 29088783, 2017). "Annexin A5 is therefore used widely as a marker for the study of apoptosis in vitro, in animal models, and even in vivo in patients with cardiovascular disease or cancer." (PMID 24592386, 2014). "Accordingly, when used for every cancer patient receiving their first course of chemo- or radiotherapy, Annexin A5 apoptosis imaging could introduce itself as a general diagnostic method to provide personalized medicine." (PMID 24216991, 2013). "Molecular imaging of Annexin A5 in the drug development stage could accelerate the search for novel anti-cancer strategies." (PMID 24216991, 2013). "99mTc-HYNIC-Annexin A5 imaging could therefore possibly identify those patients who will benefit from the anti-cancer therapy at an early stage (within 24–48 h ASOT)." (PMID 24216991, 2013). "Annexin A5-based functional imaging of apoptosis shows promise to offer a personalized medicine approach, now primarily used in genome-based medicine, applicable to all cancer patients." (PMID 24216991, 2013). "Therefore, the ability of ANXA5 to bind to PS could be exploited for therapeutic purposes in cancer patients." (PMID 36247003, 2022). "Furthermore, AnxA5 might be used for the development of selective molecular imaging probes for cancer diagnosis and disease management and importantly, for targeting drugs to the cancer cells." (PMID 29914106, 2018). "However, the detailed molecular mechanisms of ANXA5 in cancer cells are not yet fully understood." (PMID 29088783, 2017). "However, the detailed mechanism of the role of ANXA5 in cancer cells is not well understood." (PMID 29088783, 2017). "Given that survival benefits of newly developed, often expensive, cancer drugs (e.g., biologicals) are expressed in months, early diagnostics by means of Annexin A5 could provide an economically favorable way of ‘buying time’ compared to high end treatment plans." (PMID 24216991, 2013). "However, with the increasing amounts and costs of cancer medications, early assessment of efficacy of therapy by Annexin A5 imaging could offer an economic advantage." (PMID 24216991, 2013). "In summary, AnxA5-based therapy strategies may be also useful to improve immune reactions against various infectious agents which use the PS exposure as a tool to improve their survival by fooling the immune system as well as against apoptotic cancer cells." (PMID 20032867, 2009). "Muscle cell-mediated increase in IL-4 and IL-13 levels induced syncytin-1 and annexin A5 expression in human PC3 prostate cancer cells and subsequent cancer cell-cell fusion." (PMID 37016404, 2023). "Considering the new role of annexin A5 in cancer therapy, we analyzed the action of METF on annexin A5 by immunofluorescence assay." (PMID 30774659, 2019). "The increase in four multifunctional proteins, prohibitin and prohibitin 2, annexin A5 and protein S100A4, has also been documented in cancers, contributing to tumorigenic processes such as cell proliferation, metastasis, angiogenesis and immune evasion." (PMID 29662647, 2018). "For evaluation of efficacy of anti-cancer therapies, 99mTc-HYNIC-Annexin A5 imaging has to be performed both before (baseline) and after start of treatment (ASOT)." (PMID 24216991, 2013). "Annexins dysregulation has also been reported as a common feature in several cancers, and, among them, soluble ANXA5 (Annexin A5) has been described for its activity in cell membrane resealing, an essential repair machinery that promotes survival in invasive cancer cells." (PMID 37835519, 2023).
cancer (continued). "GlaS showed the same tendency as annexin A5 and slightly higher signals in cancer cell-derived m/lEVs (annexin A1+) but was not statistically significant." (PMID 36992223, 2023). "In most cancers, the signature genes were differentially methylated compared to normal tissue; in particular, genes including as representatives NCOA4, CTSL, MCUB, ANXA5 and ANGPTL2 were usually hypermethylated, while genes including PDE2A and others were usually hypomethylated." (PMID 37660060, 2023). "Here, we further investigated the binding of FITC-labeled GlaS and APC-labeled annexin A5 proteins to sEVs and m/lEVs derived from cancer and non-cancerous cells by fluorescence microscopy." (PMID 36992223, 2023). "Previously, we modified anxA5 by fusion with the XTEN288 polypeptide and were thus able to prolong blood circulation time in mice from 7 min to 1 h, which in turn allowed improved imaging of apoptosis in cancer treatment." (PMID 34405304, 2021). "The overexpressed proteins, including actinin α1 isoform (ACTN1), annexin A5 (ANXA5), cathepsin D (CTSD), F-actin-capping protein subunit β (CAPZB), inorganic pyrophosphatase (PPA1), and tubulin α1c chain (TUBA1C), are related to cellular structure, growth, or cancer cell invasion." (PMID 38249992, 2024). "Six proteins 60Sacidic ribosomal protein P2, Peroxiredoxin-2, Annexin A5, PDZ and LIM domain protein 1, Src substrate cortactin and Moesin were found as emerging proteins of the H22 cell incubated with high dose lentinan which related to cancer promotion closely." (PMID 29221118, 2017). "Notably, in our bead-based assays, both GlaS and annexin A5 proteins detected higher PS exposure on m/lEVs derived from MDA-MB-468 cells but not MDA-MB-231 cells, suggesting the high PS exposure on EVs may be cancer cell type-dependent." (PMID 36992223, 2023). "Unexpectedly, among the sEV-enriched fractions derived from the four cell types assessed, keratinocyte-derived sEVs, but not cancer cell-derived sEVs, showed significantly higher binding of APC-annexin A5." (PMID 36992223, 2023). "Thus, we further aimed to compare the binding efficiencies of annexin A5 and GlaS proteins to PS-exposing sEVs and m/lEVs, identified by CD63 or annexin A1 positivity, respectively, derived from cancer and non-cancerous cells using single EV flow cytometry." (PMID 36992223, 2023). "Thus, future studies will be needed to understand the control mechanisms of PKC-ζ protein levels by ANXA5 without transcriptional changes, and elucidate whether differences in reactivity in response to proinflammatory stimuli are affected by the basal level of PKC-ζ expression in other cancer cells." (PMID 29088783, 2017).